DMD (dystrophin)
Diseases named in the same sentence as DMD in open-access papers (continued):
Sharing a sentence is not in itself a finding about the gene and the disease.
Duchenne muscular dystrophy (continued). "Duchenne muscular dystrophy (DMD) is one of the most prevalent neuromuscular disorders and is caused by mutations in the dystrophin gene that result in loss of the key structural protein dystrophin." (PMID 32597486, 2020). "Being the most common and most severe type of muscular dystrophy, Duchenne muscular dystrophy (DMD), is caused by mutations in the X-linked dystrophin gene." (PMID 32717791, 2020). "Duchenne muscular dystrophy (DMD) is a progressive muscle wasting disorder stemming from a loss of functional dystrophin." (PMID 33092650, 2020). "Duchenne muscular dystrophy (DMD) is a progressive muscle disease caused by the loss of dystrophin, which results in inflammation, fibrosis, and the inhibition of myoblast differentiation in skeletal muscle." (PMID 32869445, 2020). "The most common type, Duchenne muscular dystrophy (DMD), affects one in 5,000 males at birth who inherit mutations in the gene encoding dystrophin, a scaffolding protein that maintains the integrity of striated muscles." (PMID 32051598, 2020). "Mutations in the dystrophin gene are linked to a severe form of muscular dystrophy known as Duchenne muscular dystrophy (DMD) or a mild form known as Becker muscular dystrophy (BMD)." (PMID 32938372, 2020). "Duchenne muscular dystrophy (DMD) is caused by the absence of functional dystrophin protein and results in progressive muscle wasting." (PMID 32109352, 2020). "In vivo studies have also been conveyed on Duchenne muscular dystrophy (DMD), a deadly neuromuscular pathology caused by the absence of the dystrophin protein and characterized by a progressive weakness of skeletal muscles." (PMID 31976201, 2020). "Cardiomyopathy is most commonly associated with Duchenne muscular dystrophy (DMD) and Becker muscular dystrophy (BMD), both X-linked recessive disorders caused by mutations in the dystrophin (DMD) gene." (PMID 31979133, 2020). "Duchenne muscular dystrophy (DMD), caused by mutations in the dystrophin gene, is characterized by progressive muscle weakness." (PMID 32927262, 2020). "Duchenne muscular dystrophy (DMD) is the most common childhood muscular dystrophy, affecting one in 5,000 male births and is caused by mutations in the X-linked DMD gene resulting in the absence or severe reduction of the dystrophin protein." (PMID 32373058, 2020). "The mdx mouse is a widely used murine model of Duchenne muscular dystrophy: both mdx mice and DMD human patients harbor mutations in the same causative gene which codes for dystrophin protein." (PMID 32381068, 2020). "First, because dystrophin absence causes Duchenne muscular dystrophy (DMD), while its reduction causes Becker muscular dystrophy (BMD)." (PMID 32813700, 2020). "For example, Duchenne muscular dystrophy (DMD) is the most common and severe form of muscular dystrophy, which is caused by mutations in the Dystrophin (DMD) gene." (PMID 33198188, 2020). "Out-of-frame or nonsense mutations in the DMD gene cause Duchenne muscular dystrophy (DMD) (OMIM#310200), a fatal progressive muscle wasting disease." (PMID 32443516, 2020). "Duchenne muscular dystrophy (DMD) is an X‐linked recessive disorder that consists of a deficiency in the dystrophin gene." (PMID 33033749, 2020). "Duchenne muscular dystrophy (DMD) is a rare X-linked severe progressive myopathy caused by mutations in the gene for dystrophin, with an estimated birth prevalence of approximately 1:5000 males." (PMID 31811595, 2020). "White matter abnormalities were also found in Duchenne muscular dystrophy (DMD), a pathological condition caused by mutations in the gene that encodes dystrophin, a protein that connects the ECM to the cytoskeleton." (PMID 32046349, 2020). "Duchenne muscular dystrophy (DMD) is a neuromuscular disorder that affects 1 out of 5,000 live male births and is caused by mutations in the dystrophin (DMD) gene." (PMID 32462052, 2020).
Duchenne muscular dystrophy (continued). "Loss-of-function mutations in the DMD gene result in the following two common forms of X-linked recessive muscular dystrophy: the more severe form of Duchenne muscular dystrophy (DMD) and the milder form of Becker muscular dystrophy (BMD)." (PMID 31754439, 2019). "Duchenne muscular dystrophy (DMD) is a genetic disorder caused by a mutation in the dystrophin gene." (PMID 31162948, 2019). "Duchenne muscular dystrophy (DMD) is the most common muscular dystrophy, whose genetic defect is identified in the X chromosome gene that encodes the intracellular protein dystrophin." (PMID 31009514, 2019). "Duchenne muscular dystrophy (DMD) is a progressive, lethal, X-linked disease of skeletal and cardiac muscles caused by mutations in the dystrophin gene." (PMID 30692507, 2019). "Mutations in the dystrophin-encoding DMD gene are associated with both severely progressive Duchenne muscular dystrophy (DMD) and less progressive Becker muscular dystrophy (BMD)." (PMID 30672725, 2019). "Duchenne muscular dystrophy (DMD) is an X-linked recessive genetic disorder caused by out of frame mutations in the dystrophin gene." (PMID 31546754, 2019). "Duchenne muscular dystrophy (DMD) is an X‐linked progressive muscle degenerative disease, caused by mutations in the dystrophin gene and resulting in death because of respiratory or cardiac failure." (PMID 30618214, 2019). "Duchenne muscular dystrophy (DMD) is a devastating muscle disease affecting one in 5,000 newborn males, in which the gene encoding the dystrophin protein is mutated." (PMID 31877123, 2019). "The dystrophinopathies Duchenne muscular dystrophy (DMD) and Becker muscular dystrophy (BMD) are X-linked muscle diseases caused by a lack of the subsarcolemmal protein dystrophin due to mutations in the dystrophin (DMD) gene." (PMID 30836656, 2019). "Duchenne muscular dystrophy (DMD) is an X-linked muscle disease affecting one in 5,000 newborn males, in which the gene encoding the dystrophin protein is mutated." (PMID 31877123, 2019). "Duchenne muscular dystrophy (DMD) is caused by the loss of dystrophin protein due to genetic defects in the DMD gene." (PMID 30281092, 2019). "Duchenne muscular dystrophy (DMD) is caused by the loss of dystrophin in muscles, leading to membrane fragility and impaired signaling." (PMID 32082161, 2019). "Nonsense and frameshift mutations of the dystrophin (DMD) gene usually cause severe Duchenne muscular dystrophy (DMD)." (PMID 31754439, 2019). "Mutation in the dystrophin gene results Duchenne Muscular Dystrophy (DMD), an X-linked fatal neuromuscular disorder." (PMID 31998814, 2019). "Duchenne muscular dystrophy (DMD) is an X-linked recessive progressive neuromuscular disease caused by DMD gene mutation which encodes dystrophin, a large cytoskeletal, structural protein for muscle membrane stability." (PMID 31890014, 2019). "Duchenne muscular dystrophy (DMD) is a muscular disorder caused by the absence or reduction of the muscle cytoskeletal protein dystrophin." (PMID 30621068, 2019). "Duchenne muscular dystrophy (DMD) is a severe muscle disorder characterised by mutations in the DMD gene." (PMID 30846748, 2019). "Duchenne muscular dystrophy (DMD) is one of the most common and serious forms of muscular dystrophy, and is caused by losing functional dystrophin protein." (PMID 31546877, 2019). "Mutations of the human dystrophin gene on chromosome Xp21 cause Duchenne muscular dystrophy (DMD), which is the most frequently occurring muscular dystrophy in humans with an incidence of 1 in 3600–6000 male births." (PMID 31077250, 2019). "Mutations in the gene encoding dystrophin result in Duchenne muscular dystrophy (DMD) and Becker muscular dystrophy (BMD)." (PMID 31266455, 2019). "Duchenne muscular dystrophy (DMD), the most common muscular dystrophy worldwide, is caused by mutations in the X-chromosome positioned DMD gene." (PMID 31434868, 2019).
Duchenne muscular dystrophy (continued). "Cardiac bodies were either differentiated from human pluripotent stem cell line CCTL14 or an induced dystrophin-deficient cell line reprogrammed from fibroblasts of a patient affected by Duchenne Muscular Dystrophy (DMD)." (PMID 31546916, 2019). "Duchenne muscular dystrophy (DMD) is caused by mutations in DMD, resulting in loss of dystrophin, which is essential to muscle health." (PMID 29858053, 2018). "Duchenne muscular dystrophy (DMD) is one of the most common and severe forms of muscular dystrophies and is caused by mutations in the dystrophin gene." (PMID 29316663, 2018). "Duchenne muscular dystrophy (DMD) is a severe muscle-wasting disease generally caused by reading frame disrupting mutations in the DMD gene resulting in loss of functional dystrophin protein." (PMID 29466448, 2018). "Duchenne muscular dystrophy (DMD) is a genetic disease associated with mutations of Dystrophin gene that regulate myofiber integrity and muscle degeneration, characterized by oxidative stress increase." (PMID 29636844, 2018). "Duchenne muscular dystrophy (DMD) is an X-linked muscle-wasting disorder caused by mutations in the dystrophin gene, with an incidence of 1 in 3500 in new male births." (PMID 29871865, 2018). "Duchenne muscular dystrophy (DMD) is a progressive and fatal X-linked neuromuscular disorder caused by mutations in dystrophin gene (DMD)." (PMID 29703249, 2018). "Duchenne muscular dystrophy (DMD) is a fatal disorder caused by absence of functional dystrophin protein." (PMID 29772070, 2018). "Duchenne Muscular Dystrophy (DMD) is a progressive and lethal disease caused by mutations of the dystrophin gene." (PMID 29546607, 2018). "Boys with Duchenne muscular dystrophy (DMD) have DMD gene mutations, with associated loss of the dystrophin protein and progressive muscle degeneration and weakness." (PMID 29843823, 2018). "Elevated circulating myomiRs levels have been described in patients with Duchenne muscular dystrophy (DMD), a pathology characterized by the loss of dystrophin protein leading to cycles of degeneration and regeneration of the muscle tissue." (PMID 29922177, 2018). "Duchenne muscular dystrophy (DMD) is an X-linked recessive disorder, caused by mutation of the DMD gene which encodes the protein dystrophin." (PMID 30544588, 2018). "Duchenne muscular dystrophy (DMD) is an X-linked neuromuscular disease caused by mutations in the gene responsible for dystrophin production." (PMID 30282911, 2018). "In particular, in Duchenne Muscular Dystrophy, an X-linked pathology related to mutation of Dystrophin (DMD), HDAC inhibitors have revealed beneficial effects." (PMID 29619865, 2018). "Duchenne muscular dystrophy (DMD) is an inherited X-linked lethal muscle wasting disease caused by a mutation in the dystrophin gene that normally encodes for a protein that links the muscle cytoskeleton through a membrane complex to the extracellular matrix." (PMID 29329193, 2018). "Duchenne muscular dystrophy (DMD) is an X-linked genetic disorder of the dystrophin (DMD) gene and is well known as a complex, disabling disorder with shortened life expectancy." (PMID 30254788, 2018). "In individuals with Duchenne muscular dystrophy (DMD), exon skipping treatment to restore a wild-type phenotype or correct the frame shift of the mRNA transcript of the dystrophin (DMD) gene are mutation-specific." (PMID 29631625, 2018). "Duchenne muscular dystrophy (DMD) is an inherited myogenic disorder due to mutations in the dystrophin gene DMD on chromosome Xp21.1." (PMID 29304097, 2018). "Duchenne muscular dystrophy (DMD) is an X-linked genetic disorder caused by mutations in the dystrophin gene (DMD, MIM# 300377)." (PMID 30498470, 2018). "The loss of several components of the DGC leads to the generation of severe myopathies, the most notable of which is the loss of functional dystrophin, which is the underlying cause of Duchenne muscular dystrophy (DMD)." (PMID 28153048, 2017).
Duchenne muscular dystrophy (continued). "Duchenne muscular dystrophy (DMD), an X-linked recessive muscle-wasting disease, is caused by a mutation in the DMD gene that encodes the dystrophin protein." (PMID 28344651, 2017). "Duchenne muscular dystrophy (DMD) is caused by a mutation in the dystrophin gene with devastating downstream effects that include muscle fibre damage and physical disability and lead to a premature death at around 20 years of age." (PMID 28378063, 2017). "Duchenne muscular dystrophy (DMD) is a neuromuscular disease that is caused by a single mutation in the dystrophin gene." (PMID 28103859, 2017). "Duchenne muscular dystrophy (DMD) is an X-linked genetic disease caused by mutations in the dystrophin gene, leading to instability of the dystrophin-glycoprotein complex (DGC) with subsequent necrosis and fibrosis." (PMID 28845212, 2017). "Mutations in the dystrophin gene underlie Duchenne muscular dystrophy (DMD), the most common and severe form of muscular dystrophies." (PMID 28750661, 2017). "In Duchenne muscular dystrophy (DMD), the loss of the dystrophin component of the dystrophin-glycoprotein complex (DGC) compromises plasma membrane integrity in skeletal muscle, resulting in extensive muscle degeneration." (PMID 28806929, 2017). "Duchenne muscular dystrophy (DMD) is a severe X-linked recessive muscle disorder caused by mutations in the dystrophin gene." (PMID 29194448, 2017). "In contrast to Duchenne Muscular Dystrophy (DMD), which results from loss of function mutations in the dystrophin gene, FSHD is linked to a gain of function of the DUX4 protein in skeletal muscles." (PMID 28273791, 2017). "Duchenne muscular dystrophy (DMD) is an X-linked recessive disorder affecting 1 in 3500 males, due to mutations in dystrophin gene leading to reduced or deficient synthesis of dystrophin, a part of the dystrophin-glycoprotein complex (DGC)." (PMID 28738778, 2017). "Duchenne muscular dystrophy (DMD) is one of the most severe types of muscular dystrophies and is caused by mutations in the dystrophin gene." (PMID 29089466, 2017). "Duchenne muscular dystrophy (DMD) is caused by mutations in the DMD gene, which codes for the dystrophin protein." (PMID 28390424, 2017). "Duchenne muscular dystrophy (DMD) is caused by loss of dystrophin expression and leads to severe ambulatory and cardiac function decline." (PMID 28899419, 2017). "Duchenne muscular dystrophy (DMD) is a lethal muscular degenerative disease caused by mutations in Dystrophin gene of X chromosome 51." (PMID 28244269, 2017). "Duchenne muscular dystrophy (DMD), resulting from mutations in the dystrophin gene on the X chromosome, is characterized by muscle degeneration and premature death." (PMID 28806929, 2017). "The most common, genetic muscle wasting disease is Duchenne Muscular Dystrophy (DMD), which is caused by mutations in the DMD gene." (PMID 29188128, 2017). "Duchenne muscular dystrophy (DMD) is a fatal muscle-wasting disease characterized by dystrophin deficiency from mutations in the dystrophin gene." (PMID 28208626, 2017). "Duchenne muscular dystrophy (DMD) is an X-linked disease caused by mutations in the DMD gene and loss of the protein dystrophin." (PMID 28526070, 2017). "The UMD-DMD France mutations database reports 2898 fully characterized mutations in dystrophin causing either Becker muscular dystrophy, Duchenne muscular dystrophy, or X-linked DCM." (PMID 29367539, 2017). "Duchenne Muscular Dystrophy (DMD) is a common form of muscle wasting seen in young boys and is caused by mutations in the dystrophin gene." (PMID 29228710, 2017). "Duchenne muscular dystrophy (DMD) is a lethal genetic disorder that most commonly results from mutations disrupting the reading frame of the dystrophin (DMD) gene." (PMID 29035327, 2017).
Duchenne muscular dystrophy (continued). "Duchenne muscular dystrophy (DMD) is an X-linked genetic disease caused by frameshift mutations in the dystrophin gene, which results in the translation of a truncated and non-functional dystrophin protein." (PMID 28573431, 2017). "X-linked Duchenne muscular dystrophy (DMD) is caused by mutations in the DMD gene, which encodes the dystrophin protein required for stability of the sarcolemma." (PMID 28491099, 2017). "Becker muscular dystrophy (BMD) is a neuromuscular disorder allelic to Duchenne muscular dystrophy (DMD), caused by in-frame mutations in the dystrophin gene, and characterized by a clinical progression that is both milder and more heterogeneous than DMD." (PMID 29167533, 2017). "Mutations in the DMD gene result in dystrophin deficiency, which causes Duchenne muscular dystrophy (DMD), the most common inherited muscle disease in childhood." (PMID 28974057, 2017). "Today, mutations in dozens of different genes are known to cause a myopathy, with Duchenne muscular dystrophy (DMD) due to mutations in dystrophin being the most frequent." (PMID 28915917, 2017). "For example, splice site mutations in the DMD gene, which encodes for dystrophin protein, results in the loss of dystrophin function that leads to Duchenne muscular dystrophy (DMD, OMIM #310200)." (PMID 28146073, 2017). "The CRISPR/Cas9 system can also be used as a therapeutic technology for treating genetic disorders such as Duchenne muscular dystrophy (DMD) by correcting the dystrophin gene mutation or cystic fibrosis by repairing the mutation in the CFTR gene." (PMID 27699445, 2017). "Duchenne Muscular Dystrophy (DMD) is an X-linked disease caused by a mutation in the DMD gene which codes for the protein dystrophin." (PMID 28763477, 2017). "Dystrophinopathies are caused by genetic mutations in the dystrophin gene that include Duchenne muscular dystrophy (DMD), Becker muscular dystrophy (BMD), and X-linked dilated cardiomyopathy (XL-DCM)." (PMID 29367543, 2017). "Duchenne muscular dystrophy (DMD) is an X-linked disorder caused by a mutation in the DMD gene, which encodes the protein dystrophin." (PMID 29326589, 2017). "Duchenne muscular dystrophy (DMD) is an incurable X-linked muscle-wasting disease caused by mutations in the dystrophin gene." (PMID 28742067, 2017). "Loss of function mutations in the DMD gene cause Duchenne muscular dystrophy (DMD), while mutations in the SGCG gene, which encodes the dystrophin associated protein γ-sarcoglycan, cause limb-girdle muscular dystrophy type 2C (LGMD 2C)." (PMID 29065150, 2017). "Duchenne muscular dystrophy (DMD) is the most prevalent neuromuscular disorders, which is characterized by progressive muscle weakness and wasting due to the absence of dystrophin protein that causes degeneration of skeletal muscle." (PMID 27783047, 2016). "Duchenne muscular dystrophy (DMD) is one of the most prevalent neuromuscular disorders and is caused by mutations in the dystrophin gene." (PMID 27055247, 2016). "For example Duchenne muscular dystrophy (DMD) is caused by a truncation in dystrophin protein due to a premature stop codon." (PMID 26612865, 2016). "Duchenne muscular dystrophy (DMD), which occurs when dystrophin was depleted by a mutation of gene coding dystrophin on the X chromosome, induces muscle necrosis, damage, fibrosis, and weakness." (PMID 26867195, 2016). "Drisapersen induces exon 51 skipping during dystrophin pre-mRNA splicing and allows synthesis of partially functional dystrophin in Duchenne muscular dystrophy (DMD) patients with amenable mutations." (PMID 27588424, 2016). "Duchenne Muscular Dystrophy (DMD) is a recessive form of muscular disorder, resulting from the dystrophin gene mutations in X-chromosome." (PMID 28979820, 2016). "Approximately one in every 3,600 live male births is affected by Duchenne muscular dystrophy (DMD), an inherited, X-linked disease caused by mutations to the gene encoding dystrophin." (PMID 27737016, 2016).